EXD2 (exonuclease 3'-5' domain containing 2)
Description:
Exonuclease that has both 3'-5' exoribonuclease and exodeoxyribonuclease activities, depending on the divalent metal cation used as cofactor. In presence of Mg(2+), only shows 3'-5' exoribonuclease activity, while it shows both exoribonuclease and exodeoxyribonuclease activities in presence of Mn(2+). Acts as an exoribonuclease in mitochondrion, possibly by regulating ATP production and mitochondrial translation. Also involved in the response to DNA damage. Acts as 3'-5' exodeoxyribonuclease for double-strand breaks resection and efficient homologous recombination. Plays a key role in controlling the initial steps of chromosomal break repair, it is recruited to chromatin in a damage-dependent manner and functionally interacts with the MRN complex to accelerate resection through its 3'-5' exonuclease activity, which efficiently processes double-stranded DNA substrates containing nicks. Also involved in response to replicative stress: recruited to stalled forks and is required to stabilize and restart stalled replication forks by restraining excessive fork regression, thereby suppressing their degradation.
Synonyms: C14orf114; EXDL2; FLJ10738
Tractability: Antibody: UniProt predicts a signal peptide or a membrane-spanning region. PROTAC: ubiquitination databases record sites on it; its protein half-life has been measured.
Gene: Protein-coding gene on chromosome 14 (69,191,498 to 69,244,020, forward strand). Ensembl gene ENSG00000081177.
Subcellular location: Mitochondrion outer membrane; Mitochondrion matrix; Nucleus; Chromosome
Subcellular location (Human Protein Atlas): Mitochondria; Intermediate filaments
Gene Ontology:
Molecular function: 3'-5' exonuclease activity; 3'-5'-DNA exonuclease activity; 3'-5'-RNA exonuclease activity; magnesium ion binding; manganese ion binding; protein binding; protein homodimerization activity; single-stranded DNA 3'-5' DNA exonuclease activity; nucleic acid binding
Biological process: DNA double-strand break processing; double-strand break repair; double-strand break repair via homologous recombination; nucleic acid metabolic process; replication fork processing; DNA recombination
Cellular component: chromosome; mitochondrial matrix; mitochondrial outer membrane; mitochondrion; nucleus; site of DNA damage
Genetic constraint (gnomAD): Loss-of-function variants: 36 observed, 60.55 expected, observed/expected ratio (o/e) 0.59, 90% interval 0.46 to 0.79. The synonymous counts are far from expectation, so gnomAD's model fits this gene poorly and the ratio says little. Missense variants: 664 observed, 789.67 expected, observed/expected ratio (o/e) 0.84, 90% interval 0.79 to 0.9. Synonymous variants: 238 observed, 307.51 expected, observed/expected ratio (o/e) 0.77, 90% interval 0.69 to 0.86.
Homologues: Orthologues: chimpanzee EXD2 (99% identical), macaque EXD2 (97% identical), dog EXD2 (90% identical), pig EXD2 (90% identical), rabbit EXD2 (88% identical), rat Exd2 (87% identical), mouse Exd2 (86% identical), guinea pig EXD2 (86% identical), tropical clawed frog exd2 (61% identical), zebrafish exd2 (54% identical), Drosophila melanogaster Exd2 (35% identical). Paralogues in human: EXD3 (18% identical).
Diseases named in the same sentence as EXD2 in open-access papers:
EXD2 is named in the same sentence as 6 diseases in open-access papers, as found by Europe PMC text mining. Sharing a sentence is not in itself a finding about the gene and the disease. The quoted sentences say what the papers report.
Fanconi anemia (1 paper, 2019). Fanconi anemia (FA) is a hereditary DNA repair disorder characterized by progressive pancytopenia with bone marrow failure, variable congenital malformations and predisposition to develop hematological or solid tumors. "EXD2 also reportedly has a critical functional link with FANCD2, the gene responsible for Fanconi anemia." (PMID 30759165, 2019).
cancer (3 papers, 2019 to 2023). A tumor composed of atypical neoplastic, often pleomorphic cells that invade other tissues. "Cells deficient in EXD2 show spontaneous chromosomal instability and are sensitive to DNA damage induced by anti-cancer agents such as IR and campthotecin, thus EXD2 is a good target for the development of a new anti-tumour treatment." (PMID 35883600, 2022). "In line with this, EXD2−/− cells display sensitivity to a range of agents that interfere with DNA replication, including clinically relevant anti-cancer drugs." (PMID 31255466, 2019). "Taken together, our findings uncover a previously unknown role for EXD2 in the replication stress response and also identifies EXD2 as a potential druggable target for cancer therapy." (PMID 31255466, 2019). "Moreover, we also uncover that loss of EXD2 is synthetic sick with BLM, DNA2 and POLD3, which could represent an attractive therapeutic target against ALT-dependent cancers." (PMID 37105990, 2023). "Finally, we show that co-depletion of EXD2 with BLM, DNA2 or POLD3 confers synthetic lethality in ALT cells, identifying EXD2 as a potential druggable target for ALT-reliant cancers." (PMID 37105990, 2023). "Here the authors demonstrate that remodelling of perturbed replication forks by the exonuclease EXD2 modulates pathway choice within the Alternative Lengthening of Telomeres mechanism and identify potentially clinically important synthetic lethal interactions in ALT cancer cells." (PMID 37105990, 2023).
EXD2 also shares sentences with these, for which no sentence is quoted: neoplasia (2 papers); chronic thromboembolic pulmonary hypertension (1); lung carcinoma (1); psychiatric disorder (1).